IL4 (interleukin 4)
Diseases named in the same sentence as IL4 in open-access papers (continued):
Sharing a sentence is not in itself a finding about the gene and the disease.
infection (continued). "The IL-4, IL-5, IL-9, and IL-13 pretreatment responses were subtracted from 1 year posttreatment responses, and correlations between the changes and pretreatment infection intensity, a proxy of the amount of worm-derived antigen exposure upon treatment, were calculated." (PMID 24357629, 2014). "However, early production of IL-4 does not necessarily correlate with susceptibility to L. major as resistant C57BL/6 mice also produce this cytokine initially until infection resolves with the development of Th1 response." (PMID 24847425, 2014). "However, because helminth-driven macrophage proliferation was independent from blood monocyte recruitment and the numbers of cells accumulating at the site of infection were significantly reduced in IL-4−/− mice 13, we tested the possibility that IL-4 was directly responsible." (PMID 25319331, 2014). "Despite the clear demonstration by multiple groups that differentiation of Bcl6+ TFH cells in vivo is independent of TH1, TH2, or TH17 differentiation pathways, how TFH cells could coordinate CSR during particular infections via IL-4 and/or IFN-γ posed something of a paradox." (PMID 24586147, 2014). "In addition, the role of IL-4 on DC and monocyte responses to infection is discussed." (PMID 25110400, 2014). "Furthermore, administration of 1 μg of recombinant IL-4 at 0 and 8 hours after infection with L. major led to increased IL-12 mRNA expression by dendritic cells (DCs) in vivo, promoted Th1 responses and rendered mice resistant to infection." (PMID 24204259, 2013). "However, in certain murine strains, IL-4 deficiency was not enough to drive substantial increases in IFNγ production or to completely prevent development of a TH2-type response during infection." (PMID 23429492, 2013). "Indeed, the characterization of the phenotype and functions of IFN-α DC has led to the concept that these cells, as opposite to conventional IL-4 DC, can resemble naturally occurring DC, rapidly generated from monocytes in response to danger signals such as infection." (PMID 23977359, 2013). "Thus, for many chronic infections (and tumors), the central (LN) generation of protective Th1 immunity may be sufficient to control infection but local IL-4-rich tissue microenvironments prevent their recruitment and limit anti-microbial function." (PMID 23991011, 2013). "IL-4 expression continued to increase over time (from 2.3 to 4.4 fold) for the wild-type strain but remained unchanged for the avirulent mutant while IL-21 transcript showed a significant increase (4.0 fold) only at 8 hours post infection with the virulent strain." (PMID 22675469, 2012). "As a hallmark of Th2 immune response, IL-4 level in allicin treated mice was comparable to that in control mice, indicating that allicin treatment did not affect Th2 immune response during early P. yoelii 17XL infection." (PMID 22873687, 2012). "From these studies, IL-4 did not seem to contribute to canine susceptibility to infection." (PMID 21845197, 2012). "Importantly, we show an association between IL-4 production and CD200R expression on T effector cells from humans infected with Schistosoma haematobium that correlated effectively with egg burden and, thus infection intensity." (PMID 22496920, 2012). "As the most abundant cell population in the skin after 4x infections wereSiglecF+ eosinophils, and R2 eosinophils sorted from total DECexpressed abundant mRNA for IL-4 and IL-13, we propose that eosinophils may be theprimary source of the copious IL-4 and IL-13 released by 4x skin biopsies." (PMID 21445234, 2011). "This highlights the role of IL4/IL-13 in driving a non-healing response and may in part explain why human males are more susceptible to this infection than females." (PMID 21245915, 2011).
infection (continued). "Thus, while susceptible BALB/c mice deficient in the ability to respond to the cytokines IL-4/IL-13 are not protected against development of cutaneous leishmaniasis caused by L. major they are totally resistant to infection with L. mexicana." (PMID 21245915, 2011). "The results showed that the inoculation of CFA prior to the infection resulted in disorganized granulomatous lesions and increased fungal replication in the lungs, liver and spleen, that paralleled with the higher levels of IL-4 when compared with the control group." (PMID 21731741, 2011). "Thus, the age-dependent ability of chicken embryos to increase IL-4 transcription upon infection might contribute to age-dependent resistance." (PMID 21603634, 2011). "However, before and after infection, the levels of IL-4, an established Th2 cytokine, was significantly higher in mice vaccinated heterologously compared to mice receiving gp63 DNA alone (p<0.001), or in association with CpG (p<0.01) and rgp63 plus CpG (p<0.001)." (PMID 21311597, 2011). "Consequently IL-4 responsive CD8+ T cells do not play a role in early susceptibility or the non-healing response following infection with L. mexicana." (PMID 21245915, 2011). "The apparent delay in cytokine responses and the lack of detectable IL-4 until day 28 post-infection in susceptible Balb/c mice may have been due to rapid consumption of these cytokines, especially IL-4, rather then lack of their production." (PMID 20625554, 2010). "The relatively low concentrations of IL-12, IL-5 and IL-4 may reflect that probably these cytokines are needed in very minute amounts, present only very temporarily or are gradually degraded or consumed by cells earlier after response to infection." (PMID 20546583, 2010). "Thus, it is possible, but we think unlikely, that reduced IL-4 expression early in infection could be involved with increased neurovirulence of vEye3." (PMID 21139679, 2010). "However, IL-4 has previously been reported to be necessary for Th1 differentiation and resistance to L. major in vivo, but only when administered exclusively during the first 8 hours of infection." (PMID 20442861, 2010). "As previous studies have shown that sterile immunity in schistosomiasis is dependent on IgE levels, eosinophils and on the Th1/Th2 balance, our laboratory decided to test whether any allelic variants in the IL4, IL5 and IL13 genes would predispose individuals to high infection levels by Schistosoma." (PMID 19471606, 2008). "These CD8+ cells displayed decreased IL-4 and TNF-αexpression during infection, but an increased level of productionof IL-10." (PMID 41365681, 2026). "From the perspective of the color scale, the expressions of IL-8, IL-1β, IL-4, IL-6, IL-2, TNF-α, IL-10, and IL-17 showed a significant upward trend as the infection duration increased." (PMID 41165313, 2025). "Complementary ELISA data demonstrated a significant augmentation in the secretion of cytokines IFN-γ, IL-4, IL-6, IL-17A, TGF-β, GATA-3, T-bet, IL-10, and TNF-α in the Pm_OMVs-infected group relative to the Pm group at 24 hours post-infection (P < 0.01)." (PMID 41306977, 2025). "In contrast, IL-4 expression in splenic cells remained significantly lower throughout the infection, resulting in elevated IFN-γ/IL-4 and IL-17/IL-4 ratios." (PMID 41156648, 2025). "QRT-PCR analysis revealed that, relative to the Pm-infected group, the expression levels of IFN-γ, IL-4, IL-6, IL-17, TGF-β, GATA-3, T-bet, RORγt, and FoxP3 genes were significantly elevated in the Pm_OMVs-infected group at 24 hours post-infection (P < 0.01)." (PMID 41306977, 2025). "Also seen were DTH and the increased production of NO and IFN-γ by spleen cells and the downregulation of IL-4, which demonstrates that an initial stimulation of a mixed Th1/Th2 response by vaccination instructs Th1 responses and resistance against a progressive infection." (PMID 40006676, 2025).
infection (continued). "We quantified serum levels of IL-4, IL-6, IL-8/CXCL-8, IL-27, CCL-2, CXCL-9, CXCL-10, and IgG using Luminex and ELISA assays during the acute and subacute phases of infection." (PMID 40711072, 2025). "IL-4 and IL-10 levels dramatically increased in the ITI and ITA infection group at 1 hpi, but significantly increased in the IN infection group at 3 hpi." (PMID 40723822, 2025). "In the mock infection group, however, the Winter PM exposure induced elevated IFN-γ, IL1-β, IL-8, IL-4, IL-5, IL-10, and VEGF-A at the 24 h timepoint." (PMID 40671793, 2025). "The relative mRNA levels of inflammatory factors were also increased after infection, including Interferon-γ (IFN-γ), Transforming growth factor-β1 (TGF-β1), Interleukin-4 (IL-4), and Interleukin-6 (IL-6)." (PMID 39927263, 2025). "In the lymph nodes, we observed significant increases in the levels of IL-4, IL-6, TNF, and IFN-γ at 22 days after infection and increases in the levels of IL-2, IL-1, and IL-10 in infected mice at 35 days." (PMID 39899646, 2025). "Among the polymorphisms associated in one cohort which were tested in different cohorts but where the association was not replicated, we have IL18 rs2043055 with CCC, IFNG rs2430561 and infection, IL4 −590 and infection, TGFB1 −509 rs1800469 and infection." (PMID 40297326, 2025). "Infection with L. (V.)guyanensis led to decreased IFN-γ in lymph nodes and increased IL-4 production in both skin and lymph nodes, whereas L. (V.)shawi infection did not significantly alter cytokine profiles." (PMID 41017914, 2025). "In the analysis of cytokines in the infected cecum, site of worm insertion, we observed a significant increase in IL-4, IL-10, TNF, and IFN-γ levels 10 days after infection." (PMID 39899646, 2025). "Infection of BALB/c and STS mice resulted in 10-500× increase of production of IFNγ IL-2, IL-4, IL-6 and IL-10 by their splenocytes, whereas strain O20 splenocytes did not produce any of these cytokines except IL-6." (PMID 41164189, 2025). "Gata3 ChIP‐seq was carried out on naïve (CD44loCD62Lhi) OTIs, after in vitro activation in the presence of IL‐4 or Notch signaling (OP9‐DL1), or primary effector OT‐Is isolated directly ex vivo 10 days after adoptive transfer and infection with A/HKx31‐OVA." (PMID 40012375, 2025). "We also tested IL-4 due to evidence that T helper 2 (Th2)–type cytokines and alternatively activated macrophages are involved in human and mouse SARS-CoV-1 and -2 infections." (PMID 40854598, 2025). "Despite sharing regulatory functions with Tregs, DNTs also secrete cytokines (IL-4, IL-17, IFN-γ, and TNF-α) to exert T helper (Th)-like activities, exhibiting protective roles across infection models in mammals." (PMID 40821846, 2025). "In vivo studies corroborate that within 24 h post-infection, early iNKT-cell activation accompanied by marked IFN-γ and IL-4 release is readily detectable." (PMID 41156830, 2025). "Here, we observed that the ratios of Th2 to Th1 cytokines, specifically anti-inflammatory cytokines (IL-4, IL-6, and IL-10) relative to IFN-γ, remained stable throughout the infection." (PMID 39061002, 2024). "Tuft cells act as an immune-privileged niche to permit viral persistence, and induction of tuft cell hyperplasia by cytokines such as IL-4 and IL-25 consequently promotes CR6 infection." (PMID 38701091, 2024). "IL-1β, IL-12 (p40), IL-4, and CCL3 levels were modulated, showing significantly lower induction during early infection (1–9 h) followed by a significant increased after 12 h." (PMID 38538626, 2024). "Their cytokine profile suggested a reduced ability to respond to SARS-CoV-2, with lower levels of IL-2, IL-4, IL-12p40, and IFN-γ, which are crucial for T-cell function and infection control." (PMID 39597537, 2024). "Type 2 cytokines such as IL-4 are well-established to induce tuft cell hyperplasia and enhance CR6 infection." (PMID 38701091, 2024).
infection (continued). "The dynamic interplay between IFN-γ and IL-4 highlights the balance between Th1/Th2 immune responses and underscores IFN-γ as a powerful indicator of immune dysregulation throughout the infection." (PMID 39408907, 2024). "Mice that healed from a primary infection also produced significantly (p < 0.01) lower levels of IFN-γ, IL-4, and IL-10 (p < 0.01) compared to control (naïve) mice." (PMID 38543944, 2024). "Surprisingly, infection of cardiomyocytes with either QRO or CI2 isolates and further stimulation with IL-4 strongly inhibited Arg-2 expression and function, which resulted in parasite loads similar to those observed in unstimulated cardiomyocytes." (PMID 39452749, 2024). "IL-10 was significantly increased in CC061 mice after MRSA infection, while IL-1β, IL-4, IL-9, IL-18, IL-23, and IL-27 were significantly increased in CC024 mice after infection." (PMID 39178306, 2024). "Macrophages from four different BVDV-free animals were incubated with ABH (or mock-treated with RPMI medium) and cultured with azithromycin, IL-4, or INF-γ before infection." (PMID 37966797, 2024). "The modulation of IL-24 by IL-4 and IFN-g in their study provides a critical link to the cytokine-driven dynamics we observed in our transcriptional profiles post-infection." (PMID 39591472, 2024). "In mice, infection with N. brasiliensis results in ILC2 and eosinophil recruitment to the FRT and increased IL-4, IL-5, and IL-33 in the tissue and/or lavage." (PMID 38277692, 2024). "Later after infection (day 10), FITC-dextran levels in baso IL-4/IL-13 (−) mice were negatively correlated with IL-17A, which was the center of a larger network of positively correlated type 1 plasma cytokines." (PMID 38780542, 2024). "During infection, basophils are activated by IL-3, IL-33, TSLP, FcεRIα cross-linking, and Notch signaling to produce IL-4, bioactive lipids, amines, and proteases." (PMID 38277692, 2024). "We observed increases in IL4 and IL10 transcription at early infection times (24-48 HPI) in the mesenteric lymph nodes." (PMID 38511816, 2024). "Following NE infection in broiler chickens, the proinflammatory factor TNF-α increased and the anti-inflammatory factors IL-4 and IL-10 decreased, disrupting the dynamic balance and promoting inflammation." (PMID 37508014, 2023). "Prior to infection, an imbalance between Th1, Th2, and Treg cytokines was observed in PFOA-exposed mice, suppressing IL-4 and IL-13 production." (PMID 37600798, 2023). "Buffaloes with both primary and secondary infection of F. gigantica also showed a mixed Th1/Th2 response in serum with elevated IFN-γ, IL-4, IL-5, and TGF-β during the early stages of infection." (PMID 38149297, 2023). "The colonic cytokine contents were analyzed, and it was detected that CR infection promoted the pro-inflammatory factors IL-1β, TNF-α, IL-6, and IL-17A (p < 0.01), as well as the anti-inflammatory factors IL-4 (p > 0.05) and IL-10 (p < 0.01)." (PMID 37111225, 2023). "Studies reported that serum TNFα was the first elevated cytokine due to LI infection, followed by the gradual increase in the secretion of IFN-γ and IL-6, while the serum concentrations of IL-10, IL-4, and TGFβ decreased." (PMID 37372164, 2023). "Given the impact of IL-4 on BCG-induced MINCLE expression in vitro, we next used intraperitoneal infection of mice with BCG for analysis of MINCLE regulation by IL-4 in vivo." (PMID 36753434, 2023). "In analyzes of lung homogenates 3 days post infection, BALB/c mice had higher protein levels of IP-10, IL-1β, TNF-α, M-CSF, IL-4, IL-12, IL-15 and IL-17." (PMID 36810092, 2023). "We observed increased levels of circulating IL-4 and IL-13 in animals that succumbed to lethal EVD, compared to relatively low levels of IL-13 in animals that survived infection." (PMID 36914721, 2023). "IL-1β, IL-12 (p40), IL-4, and CCL3 levels were modulated, showing significantly lower induction during early infection (1–9 hrs) followed by a significant increased after 12hrs." (PMID 37790429, 2023).
infection (continued). "Infection of mice with BCG upregulated MINCLE on myeloid cells, which was inhibited by IL-4 plasmid injection and by infection with the nematode Nippostrongylus brasiliensis in monocytes." (PMID 36753434, 2023). "Few genes were modulated at 31 dpi in gastrohepatic lymph nodes from animals that survived after infection with the culture-adapted strain E75CV1: three upregulated (IFN-γ, IL-23, NFκβ) and two downregulated (IL-1β, IL-4)." (PMID 36680273, 2023). "A simultaneous elevation of cytokines (IFN-γ and IL-4), which peaked at day 14 post-vaccination, may play a vital role in immune regulation, host defense against bacterial pathogens and protection at an early infection stage and thus complement the humoral immunity." (PMID 37779705, 2023). "Decreased production of IL-21 and IL-4 has been reported with human ageing, impairing memory CD4+ T cell responses to infection and vaccination efficacy." (PMID 37106796, 2023). "In another study, upregulation of Th1 cytokines [IFN-γ, interleukins (IL)-2 and IL-12p40] and Th2 cytokines (IL-4, IL-5, IL-13 and IL-10) was thought to play a crucial role in driving cellular immune responses against IBDV in the acute phase of infection." (PMID 37744374, 2023). "When the infection progresses, a Th2 response is amplified in conjunction with suppression of Th1 response with reduced IFN-γ and increased IL-4 levels." (PMID 38149297, 2023). "Our findings are consistent with previous data showing that C57BL/10 mice infected with L. amazonensis, a closely related species to L. mexicana, express low or lack mRNA levels of IL-4, IL-10, and TGF-β in lymph nodes during the late phase of the infection." (PMID 37691941, 2023). "At visit 1, increased levels of IL-4 and IL-5 were observed in patients who required ICU admission (Group 2), but these levels had fallen one month after the infection (visit 2) (p = 0.039 and p = 0.011, respectively)." (PMID 36975498, 2023). "A “two-signal” model for viral reactivation was postulated, as exogenous IL-4 and IFN-γ-blockade reactivated latent murine gammaherpesvirus-68 (MHV68) infection in vivo, which required macrophage IL-4-receptor-expression." (PMID 39816832, 2023). "On day 3, 7 and 14 after infection, serum levels of IgA and cytokines (IFN-γ, IL-4 and IL-6) were measured." (PMID 37943403, 2023). "Similar to N/TERT2G cells, PHFK treated with either IL-4/13 or TJDP demonstrated larger plaques at day 3 and significantly increased the numbers at day 5 post-infection." (PMID 35456017, 2022). "During the whole infection time, IFN-γ played a role mainly before 90 dpi and anti-inflammatory factor IL-4, IL-5 and IL-10 were up-regulated at or after 90 dpi, indicating a response shift from Th1-orientation to Th2-orientation." (PMID 35639780, 2022). "Protein and mRNA levels of IL-6 and IL-1β were significantly reduced in ASO MIR99AHG treated BMDMs compared to controls following IL-4/IL-13 stimulation and Mtb HN878 infection." (PMID 35895506, 2022). "It has also been shown that host immune response genes, including IL-4, CXCL10, IL-6, TNFα and IFNγ, are more active with NiV Malaysia infection compared to NiV Bangladesh." (PMID 35632678, 2022). "The results showed that the levels of IL-4, IFN-γ, and TNF-α increased, and IL-10 decreased after infection with T. gondii." (PMID 36245502, 2022). "As expected, there was a marked increase in the frequency of IL-4-producing CD4+T cells in the blood (P<0.001), LN (P<0.01), and spleens (P<0.001) of WT rats following infection with S. japonicum." (PMID 35584107, 2022). "As previously reported, the expression of IL-4 mRNA was comparable in C57BL/6 and BALB/c mice during this early infection period." (PMID 35894051, 2022). "According to the authors, the administration of IL-12 increased mice resistance to the infection by a possible initial increment in lymphocytic IFN-γ production and by downregulating the expression of IL-4." (PMID 36678397, 2022).